RCOR3 (REST corepressor 3)
Description:
May act as a component of a corepressor complex that represses transcription.
Synonyms: FLJ10876
Tractability: Small molecule: a structure with a bound ligand is known; a high-quality ligand is known. PROTAC: UniProt records ubiquitination sites on it; ubiquitination databases record sites on it; its protein half-life has been measured.
Gene: Protein-coding gene on chromosome 1 (211,258,377 to 211,316,385, forward strand). Ensembl gene ENSG00000117625.
Subcellular location: Nucleus
Subcellular location (Human Protein Atlas): Nucleoplasm; Cytosol
Gene Ontology:
Molecular function: protein binding; transcription corepressor activity
Biological process: negative regulation of DNA-templated transcription; regulation of transcription by RNA polymerase II
Cellular component: cytosol; nucleoplasm; transcription repressor complex; histone deacetylase complex; transcription regulator complex; nucleus
Genetic constraint (gnomAD): Loss-of-function variants: 10 observed, 46.8 expected, observed/expected ratio (o/e) 0.21, 90% interval 0.13 to 0.36. The upper end of that interval is the gene's LOEUF score, 0.36, which puts it in group 1 of 6, group 1 being the genes least tolerant of losing a copy. Missense variants: 452 observed, 658.68 expected, observed/expected ratio (o/e) 0.69, 90% interval 0.63 to 0.74. Synonymous variants: 204 observed, 228.71 expected, observed/expected ratio (o/e) 0.89, 90% interval 0.8 to 1.
Homologues: Orthologues: chimpanzee RCOR3 (100% identical), dog RCOR3 (99% identical), macaque RCOR3 (99% identical), pig RCOR3 (99% identical), mouse Rcor3 (97% identical), rat Rcor3 (90% identical), rabbit RCOR3 (88% identical), guinea pig RCOR3 (85% identical), tropical clawed frog rcor3 (81% identical), zebrafish rcor3 (74% identical), Drosophila melanogaster CoRest (37% identical), Caenorhabditis elegans F28F8.7 (11% identical), and 3 more. Paralogues in human: RCOR2 (55% identical), RCOR1 (50% identical), ZNF541 (18% identical), MIDEAS (17% identical), TRERF1 (15% identical).
Diseases named in the same sentence as RCOR3 in open-access papers:
RCOR3 is named in the same sentence as 9 diseases in open-access papers, as found by Europe PMC text mining. Sharing a sentence is not in itself a finding about the gene and the disease. The quoted sentences say what the papers report.
glaucoma (1 paper, 2023). Increased pressure in the eyeball due to obstruction of the outflow of aqueous humor. "However, its target gene RCOR3 showed poor ability to distinguish POAG from non-glaucoma individuals (AUC = 0.755)." (PMID 37940950, 2023). "HSP90AB1, RCOR3, SCAMP2 and SLC64A (AUC < 0.8) showed poor ability to distinguish POAG from non-glaucoma individuals." (PMID 37940950, 2023).
tumor (2 papers, 2019 to 2023). "GSCALite analysis showed that each member of RCORs exhibited different activation or inhibition in common signaling pathways, indicating that RCOR1, RCOR2, RCOR3 probably work independently or competitively in tumor progression so that leading to opposite effect on the prognosis of cancer patients." (PMID 37342230, 2023). "RCOR1 and RCOR2 expression differed significantly among tumor stages, whereas no significance exists between RCOR3 expression and tumor stages, we still noticed that RCOR3 expression elevated progressively among stage II, III, and IV." (PMID 37342230, 2023).
cancer (1 paper, 2023). A tumor composed of atypical neoplastic, often pleomorphic cells that invade other tissues. "According to our study, in HCC, we extracted RCORs-miRNA-lncRNA pairs, such as RCOR1-hsa-miR-9-3p-CT62, RCOR2-hsa-miR-1343-3p-LINC02693, RCOR3-hsa-miR-128-3p, etc., offering potential targets for cancer therapy." (PMID 37342230, 2023). "Besides, both RCOR1 and RCOR3 displayed highest expression in LAML, whereas RCOR2 was obviously upregulated in UCS and LGG, indicating that RCORs expression may varied among different cancer types." (PMID 37342230, 2023).
RCOR3 also shares sentences with these, for which no sentence is quoted: breast carcinoma (1 paper); colorectal cancer (1); intrahepatic cholangiocarcinoma (1); macrosomia (1); prostate carcinoma (1); prostate tumours (1).